RPS20P10 (ribosomal protein S20 pseudogene 10)
Gene: Transcribed processed pseudogene on chromosome 2 (71,984,182 to 71,984,434, reverse strand). Ensembl gene ENSG00000233971.
Diseases named in the same sentence as RPS20P10 in open-access papers:
RPS20P10 is named in the same sentence as 1 disease in open-access papers, as found by Europe PMC text mining. Sharing a sentence is not in itself a finding about the gene and the disease.
RPS20P10 shares sentences with these, for which no sentence is quoted: cannabis dependence (1 paper).